TF (transferrin)
Diseases named in the same sentence as TF in open-access papers (continued):
Sharing a sentence is not in itself a finding about the gene and the disease.
tumor (continued). "As an example, dual-receptor GNPs, functionalized both with FGF and transferrin, were able to cross the BBB more efficiently and accumulate more intensely in the tumor with respect to untargeted GNPs or transferrin-only targeted GNPs." (PMID 29867737, 2018). "Let-7i rs10877887 is located in the promoter region of miRNA let-7, which was a well-known tumor suppressor of multiple cancers and incorporates a CpG island, TF biding sites, and DNase peak." (PMID 30619739, 2018). "In vivo, improved bioavailability of tocotrienols were reported with NLCs while marked tumor regression was observed with transferrin-targeted niosomes." (PMID 30534071, 2018). "In vivo, intravenous injection of transferrin-bearing niosomes entrapping tocotrienol led to 60% tumor regression on mice bearing A431 epidermoid carcinoma tumors." (PMID 30534071, 2018). "For example, transferrin–functionalized graphene quantum dots were developed to track and image tumor cells expressing the TfRs." (PMID 29755355, 2018). "There were 266 of 769 HC lncRNA/TF pairs were significantly correlated in at least one tumor type, involving 159 TF genes and 253 lncRNAs." (PMID 30229065, 2018). "Most recently, a drug-induced transferrin self-assembly strategy is developed to fabricate tumor-targeted NPs for fluorescence and PA dual-modal imaging-guided PTT of glioma." (PMID 29755355, 2018). "In a further study, transferrin-bearing multilamellar vesicles entrapping α-tocotrienol led to complete tumor eradication of up to 60% of B16F10 tumors." (PMID 30534071, 2018). "The moieties include monoclonal antibodies (mAb) and other proteins (such as transferrin), nucleic acids (aptamers), small molecules (folic acid), polymers (hyaluronic acid) and peptides (proteins), which are over-expressed on tumour cells only." (PMID 30322132, 2018). "The effect of TF in tumor cell biology in vitro as well as tumor progression in vivo was also examined." (PMID 28106852, 2017). "Several tumor cell lines from different tumor types were tested for their TF expression, and A549 cells were chosen for further procoagulant activity evaluations due to their relatively high TF expression." (PMID 28106852, 2017). "TF-HA-CMC-PLGA NPs has characteristics of enhanced cellular uptake by TFR positive tumor cells, efficient photodynamic antitumor therapy and minimal side effects." (PMID 29209206, 2017). "The transferrin-targeting nanoparticle delivery system that carries the tumor suppressor microRNA-1, efficiently delivered miR-1 and inhibited migration of GBM patient-derived GSC-enriched spheres." (PMID 29088799, 2017). "Another study from an experimental metastatic model also suggested coagulation induced by tumor-derived TF facilitated premetastatic niche formation in a monocyte/macrophage dependent manner." (PMID 28106852, 2017). "Tumor uptake of the radiotracer exceeded that of blood pool at 4 hours, demonstrating the rapid dissemination of transferrin into peripheral tissues." (PMID 28893116, 2017). "The antibody targeting transferrin not only augmented uptake by the tumor based on in vitro data but also increased transport of the antibody-shRNA complex through the blood-brain barrier." (PMID 29218233, 2017). "Nevertheless, in the primary tumor site, the understanding of coagulation induced by TF within tumor microenvironment remains incomplete." (PMID 28106852, 2017). "In this context, present study explores the feasibility of tumor targeting using transferrin (Tf) as a targeting ligand." (PMID 28122339, 2017). "Other investigators have found that transferrin coupled to NP enhanced the specificity and potency of the NP within the tumor." (PMID 29218233, 2017). "In support of this deduction, works from other researchers demonstrated that TF expression in tumor cells is dispensable for in vitro proliferation but specifically impacts the biology of tumor growth in vivo." (PMID 28106852, 2017).
tumor (continued). "Transferrin was employed as a targeting ligand and the formulation exhibited enhanced antitumor efficacy in tumor-bearing murine model." (PMID 28230749, 2017). "Transferrin (Tf) is a glycoprotein used to improve targeting efficiency for the tumor cells which overexpress the Tf-receptor by grafting to nanoparticles made of poly(L-lysine), polyethyleneimine, cyclodextrin, or polyamidoamine." (PMID 28261093, 2017). "Comparing the performance of constructed platforms in targeted cells, the increased lethal effects of systems bearing transferrin is observed, indicating that the ligand increases the platform affinity towards the tumor cells." (PMID 28166290, 2017). "In the tumor microenvironment, the role of TF-induced coagulation in tumor progression remains to be fully elucidated." (PMID 28106852, 2017). "The inhibitory effect of TF high dose (15g/k) on tumor growth in mice was better than that of CTX, and the inhibitory effect of TF medium and low dose (7.5g/kg, 3.75g/kg) on tumor growth was less than CTX." (PMID 28903343, 2017). "To further assess the role of TF in tumor development in vivo, we subcutaneously inoculated 1.0 × 106 A549-vec cells or A549-shTF cells into the right flank of nude mice." (PMID 28106852, 2017). "Using TF-knockdown lung tumor cells, we showed that TF is the dominant component of procoagulant activity but is dispensable in the cellular biology of tumor cells." (PMID 28106852, 2017). "The overexpression of TF and its isoform, asTF, was found in a spectrum of different tumor types and was correlated with poor prognosis in clinical studies." (PMID 28106852, 2017). "In contrast to our findings, several studies have reported that TF promotes tumor cell proliferation through protease-activated receptors (PARs) signaling and integrin signaling." (PMID 28106852, 2017). "Although 68Ga-transferrin can accumulate in abscesses with abnormal vascularity, several lines of evidence show that uptake in the tumor microenvironment is due to specific receptor binding rather than the enhanced permeability and retention effect (EPR)." (PMID 28893116, 2017). "The tumor inhibition rates of TF high, medium and low dose (15g/kg, 7.5g/kg, 3.75g/kg) were 64.07%, 53.64% and 46.69%." (PMID 28903343, 2017). "This study suggests that tumor-derived TF induces coagulation within the tumor microenvironment, which contributes to complement activation and subsequent MDSC recruitment, leading to tumor progression." (PMID 28106852, 2017). "Histological examination of tumor tissue demonstrated that TF-HA-CMC-PLGA NPs induced extensive tumor damage." (PMID 29209206, 2017). "The strategy of utilizing TF/TFR as a drug targeting carrier is based on the overexpression of TFR on the surface of tumor cells." (PMID 29209206, 2017). "In view of this situation, it seems necessary to verify the targeting ability of TF-HA-CMC-PLGA NPs on A549 tumor-bearing nude mice model." (PMID 29209206, 2017). "We took an alternative approach to assessing tumor metabolism and developed two NIR fluorescent probes, BombesinRSense 680 (BRS-680) and Transferrin-Vivo 750 (TfV-750), for tumor metabolic imaging." (PMID 28792505, 2017). "The immunostaining of many cancer tissues from different histological origins revealed high tissue factor (TF) expression in tumor tissues, which has been reported to contribute to the hypercoagulant state of cancer patients." (PMID 28106852, 2017). "To illustrate, neoplasms patients achieved lower efficacy in hemoglobin increase, but higher efficacy in transferrin saturation >20%." (PMID 28758033, 2017). "We report that down-regulation of TF expression resulted in decreased fibrin deposition as well as complement activation within the tumor microenvironment." (PMID 28106852, 2017). "The tumor inhibition rates with high, medium and low dose of TF were 64.07%, 53.64%, 46.69%, respectively." (PMID 28903343, 2017).
tumor (continued). "The finding that TF expression correlated with differentiation of the tumor and the survival further confirmed the importance of this protein in association with PDAC." (PMID 27495108, 2016). "Numerous modifications of polymers have been discovered to target tumor cells including folic acid, transferrin, epidermal growth factor (EGF) and the tripeptide arginine-glycine-aspartate RGD." (PMID 27735873, 2016). "The conjugation of Cy5.5 to transferrin enabled additional fluorescence imaging and generated greater sensitivity in the acquisition of molecular changes in tumor site." (PMID 27223075, 2016). "Mild reaction conditions were developed to link human transferrin and tumor-targeting antibodies to the outer membrane of KabC-platelets." (PMID 27049725, 2016). "Second, the particles can be decorated with a specific functional group such as antibody, transferrin, cyclic pentapeptide (cRGD), and folic acid so that they can be actively targeted to specific tumor tissues for uptake into tumor cells." (PMID 27652265, 2016). "TF-conjugated nanoparticles can selectively deliver anticancer drugs to tumor cells overexpressing TFR through TFR-mediated endocytosis." (PMID 27377918, 2016). "This study suggests that transferrin-coupled KabC-platelets bind to tumor cells that over-express the transferrin receptor where they are retained through multiple interactions." (PMID 27049725, 2016). "Intravenous administration of transferrin-bearing vesicles loaded with TRF induced tumor regression and improvement of animal survival in a murine xenograft model and was well tolerated by animals." (PMID 26137487, 2015). "SRL displays specificity for TF antigen (Galβ1→3GalNAc-α-Ser//Thr) expressed in all cancer types and has tumour suppressing effects in vivo." (PMID 26076107, 2015). "In the in vivo component of the present study, TF-LP demonstrated the best inhibitory effect on tumor growth in the A549 tumor-bearing mice." (PMID 25663858, 2015). "To do so, we propose to replace the transferrin moiety by other promising tumor-targeting ligands of the same family that have been shown to have intrinsic anti-tumoral activity, such as lactoferrin and lactoferricin." (PMID 25933695, 2015). "This novel formulation not only significantly improved tocotrienol uptake by transferrin-expressing tumor cells but also improved the in vitro therapeutic efficacy of free tocotrienol from 17- to 72-fold depending on the cell line." (PMID 26137487, 2015). "Our results showed that the thermosensitive artemisinin and transferrin-loaded magnetic nanoliposomes would be an effective choice for tumor-targeted therapy, due to its suitable stability and high effectiveness." (PMID 24887240, 2014). "Transferrin (Tf) is one of the most widely used tumor-targeted ligands because Tf receptors (TfRs) are over-expressed on malignant cells and play a key role in cellular iron uptake through the interaction with Tf." (PMID 25400528, 2014). "In the present study, we report that endothelial integrin α3β1 does indeed interact directly with TF-Ag/Gal-3 complexes and significantly increases the strength of tumor/endothelial cell adhesion." (PMID 24675526, 2014). "A number of authors have used Ce6 for conjugation with either tumor specific monoclonal antibodies, or in peptide mediated approaches with insulin or transferrin." (PMID 25111655, 2014). "Addition of transferrin to 10B plus iodine contrast agent coloaded liposomes allowed a 3.6-fold higher 10B concentration in tumor tissues over untargeted coloaded liposomes." (PMID 23533772, 2013). "In parallel to these studies, conjugation of transferrin to doxorubicin-loaded liposomes resulted in higher doxorubicin delivery to tumors and tumor growth inhibition over untargeted doxorubicin-loaded liposomes." (PMID 23533772, 2013). "In this preclinical model, transferrin-conjugated PEG liposomes provide selective uptake of 10B by the tumor tissue, thereby increasing tumoricidal activity with BNCT." (PMID 22069714, 2011).
tumor (continued). "Response to hypoxia is mediated by the hypoxia-inducible factor 1α (HIF-1α), which is known to regulate the functions of some tumor-associated proteins, such as vascular endothelial growth factor (VEGF), transferrin, and DEC1." (PMID 21829689, 2011). "Proposed products include whole transferrin, adducts or conjugates (e.g. to diphtheria toxin for tumor therapy), and protein fusions." (PMID 21083917, 2010). "The mechanisms of antineoplastic activity of gallium are complex and can be viewed as a two-step process in which the first step involves the targeting of gallium (as transferrin-gallium) to transferrin receptor-bearing tumor cells." (PMID 20623028, 2010). "Using a screening set of 18 tumor samples (from eight control patients and 10 TF patients), a 47-gene signature discriminating between TF and control samples was identified using cDNA arrays." (PMID 18928543, 2008). "We then investigated the expression of ESR1/ERα and that of the five following top-ranked genes (MET, FOS, SNCG, IGFBP4, and BCL2) by RTQ-PCR on the initial set of 18 tumor samples (eight control and 10 TF)." (PMID 18928543, 2008). "A common system used is that of the transferrin (Tf) receptor (TfR) for binding and cell entry, as these TfRs are over-expressed by a variety of tumour cells and are widely being investigated for tumour-targeted drug delivery." (PMID 16792817, 2006). "Our data suggest that thrombin enhances TF gene expression and protein synthesis in tumour cells in vitro via PKC activation." (PMID 9820166, 1998). "In blood, development of the tumour produced an increase in ceruloplasmin and a decrease in iron-transferrin." (PMID 187210, 1976). "As a result, TFRC is activated, facilitating tumour cells to absorb iron bound to transferrin." (PMID 41153383, 2025). "In males, the tumor size correlated with lower levels of iron (ρ = −0.32, p = 0.046), which inversely correlated also with the pT stage (ρ = −0.35, p = 0.044), which was itself inversely correlated with % transferrin saturation (ρ = −0.30, p = 0.048)." (PMID 40507970, 2025). "To test whether HSAT expression could modulate TF/FVIIa activity in tumor cells, we assayed TF/FVIIa activity on mouse PDAC cells using a modification of a previously published protocol." (PMID 40924474, 2025). "Similarly, carbon dots conjugated with folic acid or transferrin can selectively accumulate in cancer cells expressing the corresponding receptors, producing strong fluorescence contrast and facilitating early tumor detection." (PMID 41470537, 2025). "These permanent changes driven by TF activity underscore a pivotal finding that even in the absence of new genomic alterations, there may be vast phenotypic changes affecting a tumor’s structure and function." (PMID 39514406, 2025). "However, because Fe2+ is generally oxidized in the internal environment and has a limited uptake rate due to its low transferrin combination ability, the direct application of Fe2+ is ineffective in inducing tumor ferroptosis." (PMID 40530387, 2025). "Lower % transferrin saturation may reflect iron sequestration or restricted availability, potentially contributing to tumor-driven metabolic adaptations." (PMID 40507970, 2025). "Notably, unmodified nanoparticles were more effective at inhibiting tumor cell growth than transferrin-conjugated (TfR) nanoparticles." (PMID 40860814, 2025). "Importantly, treatment with BEVs‐LCTP‐siSLC7A11 not only impaired tumorigenesis but also activated ferroptosis pathways, as evidenced by altered expression levels of SLC7A11 and transferrin in tumor and metastatic tissues." (PMID 41030277, 2025). "Collectively, the CD of TCR is found to be an important target for anti-tumor treatment, and its interaction with transferrin may have immune-checkpoint-like functions." (PMID 39810853, 2025).
tumor (continued). "Indeed, vitamin E has been found to exert a pro-tumorigenic effect by suppressing oxidative ferroptosis marks triggered by the iron carrier transferrin knockdown in circulating tumor cells originating from patients with metastatic melanoma." (PMID 40227202, 2025). "In addition, we attempted to dissect the transcriptional differences among tumor subclones, potential TF regulators during the leptomeningeal metastasis process in single patient." (PMID 40883281, 2025). "Research has shown that abnormal iron homeostasis in tumor cells is manifested mainly by increased expression of ferritin, transferrin, transferrin receptor, and hepcidin, leading to increased iron absorption and storage and ultimately causing iron overload in tumor cells." (PMID 41551149, 2025). "Transferrin primarily mediates the mitogenic activity of neutrophils on tumor cells." (PMID 40528159, 2025). "Similarly, transferrin has been employed to target transferrin receptors on glioma and endothelial cells to facilitate drug uptake into the tumor compartment." (PMID 40918539, 2025). "Tissue Factor (TF, CD142), expressed in extravascular cells (fibroblasts, smooth muscle), is implicated in tumor progression, therapy resistance, and enhanced pro-angiogenic signaling, with TF+ EVs fostering a pro-tumor microenvironment." (PMID 39594703, 2024). "They showed significant anti-tumour activity both in vitro and in vivo with the anti-TF/CD3 TCB." (PMID 39105809, 2024). "Additionally, UCMSs-MC540-TF, a nanovaccine using TF as the antigen, suppressed tumor growth and extended the lifespan of tumor-bearing BALB/c mice compared with PDT or immunotherapy." (PMID 39334825, 2024). "Tumor cells undergoing TF brachyury-mediated EMT to overexpress transmembrane glycoprotein mucin-1 (MUC-1) will exhibit reduced susceptibility to CTL killing even with normal levels of HLA class I, antigenic peptides, and components of the antigen presentation." (PMID 39766230, 2024). "Overall, a diverse range of immunotherapies utilising anti-TF mAb to target tumours are currently being researched and show promise, thus the addition of new sequences to the library of successfully expressed and functional anti-TF scFv will further aid research." (PMID 39105809, 2024). "Elevated levels of post-operative serum transferrin, iron, and TS% consistently demonstrated statistically significant associations with better CSS and OS after adjustment for age, sex, cancer stage, and tumour site." (PMID 39191894, 2024). "Using ROS-regenerative nanophotosensitizers coated with a tumor-targeting transferrin-titanocene complex (TiO2-TC-Tf) and radiolabeled 2-fluorodeoxyglucose (18FDG), we found that adherent dying cells maintained metabolic activity with increased membrane permeabilization." (PMID 38558990, 2024). "Overall, the reduction in transferrin significantly obstructs tumor formation." (PMID 38921444, 2024). "Similar to transferrin, ferrin can bind to TfR1 on endothelial and tumour cells." (PMID 38919382, 2024). "SREBP-2 directly promotes transferrin expression, which lowers intracellular iron levels, ROS stress, and lipid peroxidation, thereby inhibiting ferroptosis to boost the survival and drug resistance of circulating tumor cells." (PMID 38921444, 2024). "Mice injected with [45Ti]Ti-oxalate had a higher uptake in the tumor than that of [45Ti]Ti-MSN likely due to the affinity of Ti with transferrin which may help regulate the delivery of Ti to the tumor site." (PMID 38675439, 2024). "In certain malignant tumors, elevated TF expression is observed in both serum and tumor tissues." (PMID 37046617, 2023). "Additionally, one of the key mechanisms by which the TF-thrombin-PAR-1 signaling axis in tumor cells facilitates PDAC growth and disease progression is the suppression of antitumor immunity." (PMID 37046617, 2023).